EGFR (epidermal growth factor receptor)
Diseases named in the same sentence as EGFR in open-access papers (continued):
Sharing a sentence is not in itself a finding about the gene and the disease.
penile cancer (13 papers, 2011 to 2025). A primary or metastatic malignant neoplasm that affects the penis. "Moreover, an association between EGFR overexpression and poor prognosis of penile cancer has been described, especially with disease recurrence and reduced survival." (PMID 32942549, 2020). "Given genomic profiling demonstrating the presence of EGFR alterations, EGFR-directed therapies have been utilizing in treatment recurrent or advanced penile cancer." (PMID 39882447, 2024). "Although several case reports have demonstrated potential clinical efficacy in patients whose tumors harbor EGFR or BRCA2 mutations, prospective data lacks in oncogenic driver mutated penile cancer." (PMID 39882447, 2024). "A subsequent case series evaluated treatment outcomes with EGFR-directed therapies in 3 patients with advanced penile cancer whose cancers were refractory to chemotherapy." (PMID 39882447, 2024). "Cetuximab is an epidermal growth factor receptor (EGFR) inhibitor frequently used in the treatment of penile cancer." (PMID 36039252, 2022). "One example for targeted therapeutic agents in penile carcinoma addressed growth factor receptors with tyrosine kinase activity, particularly the anti-epidermal growth factor receptor (EGFR) by the use of respective monoclonal antibodies." (PMID 33868995, 2021). "EGFR overexpression turned out to be a common feature of penile carcinomas, independently of histologic grade or subtype, and HPV presence." (PMID 33868995, 2021). "Evidence of activity of anti-EGFR agents in advanced penile cancer was originally reported when administered as single agent or in combination with chemotherapy." (PMID 28066240, 2016). "In one study of penile cancer patients, p-EGFR was expressed in 25% of 148 samples, but an independent prognostic impact was not reported." (PMID 23819610, 2013). "In a recent study, the KRAS-BRAF pathway, which is a major EGFR dependent pathway, was examined in penile carcinomas." (PMID 24077122, 2013). "Activated EGFR is significantly associated with phosphorylated nuclear and cytoplasmic Akt, indicating that EGFR is an upstream regulator of PI3K-Akt signalling in penile cancer." (PMID 21407808, 2011). "HPV-negative tumours tend to express significantly more activated EGFR than HPV-positive cancers and this expression correlates with activated Akt protein, indicating EGFR as an upstream regulator of Akt signalling in penile cancer." (PMID 21407808, 2011). "Penile cancer highly expresses epidermal growth factor receptor (EGFR)." (PMID 35740662, 2022). "Previous studies that reported more than 90% of penile cancer showed high EGFR expression." (PMID 35740662, 2022). "Currently, the role of anti-epidermal growth factor receptor (anti-EGFR) targeted therapy (cetuximab, panitumumab, and dacomitinib) in the treatment of advanced penile cancer is investigational (recommendation, LE: 1b-) as the available literature is still limited." (PMID 33104884, 2020). "More clinical studies are needed to investigate whether anti-EGFR therapy can play a role in the treatment of advanced penile cancer." (PMID 32942549, 2020). "From a biological perspective, EGFR appears a promising target in penile cancer, as it is universally expressed and frequently phosphorylated, but infrequently amplified, or mutated, while mutations of downstream signaling proteins (such as KRAS/BRAF) are rare." (PMID 28066240, 2016). "The EGFR pathway is likely to serve as an important therapeutic target in coming years, with panitumumab (an EGFR antibody) shown to exhibit some biological activity in the few cases of advanced penile cancer patients it was employed." (PMID 24077122, 2013). "Targeted drugs successfully used in other SCC organ sites may serve a potential role in penile cancer as shown in the preliminary reports employing EGFR antibodies (discussed further in the section below)." (PMID 24077122, 2013).
penile cancer (continued). "Epidermal growth factor receptor (EGFR) is strongly expressed in penile carcinoma tissue whereby suggesting it may play an important role in penile carcinogenesis." (PMID 24077122, 2013). "Thus, EGFR would be a good target molecule for NIR-PIT in penile cancer." (PMID 35740662, 2022). "Indeed one case report has described the activity of panitumumab as second-line therapy in penile cancer, which exhibited amplified EGFR with no K-Ras mutations." (PMID 23819610, 2013). "Epidermal growth factor receptor (EGFR) is highly expressed in SCC and has been targeted for therapy in penile cancer." (PMID 39996908, 2025). "Since the effect of anti-EGFR treatment highly depends on intact KRAS, these findings are very meaningful for penile cancer treatment." (PMID 24077122, 2013). "While chronic inflammation seems to be the most important pathway of carcinogenesis in penile cancer, penile cancer shares the activation of COX-2, PGE2 as well as EGFR with most of the other SCC tumor phenotypes." (PMID 24077122, 2013). "Studies on small series of penile cancer show frequent overexpression of EGFR, but there is no data on other HER receptors in penile cancer." (PMID 21407808, 2011). "Our hypothesis-generating study showed that p-EGFR can be a powerful tool for prognosis discrimination of penile cancer patients with limited or no lymphnode involvement." (PMID 23819610, 2013).
prostate (13 papers, 2008 to 2025). "Moreover, Dyn2 is required for endocytosis of several oncogenic receptors such as EGFR and Her2 34,35, many of which have been implicated in prostate carcinogenesis." (PMID 24402972, 2014). "Overall, EGFR amplification was detected in cfDNA from 8.5% of patients (2,423 of 28,584), most commonly in colorectal (16.3% [458 of 2,807]), non–small-cell lung (9.0% [1,096 of 12,197]), and genitourinary cancers (8.1% [170 of 2,104])." (PMID 31058253, 2019). "However, cell lines show 1–2 times higher expression of EpCAM and EGFR, considering all tumour types together or colon, breast and prostate tumoursindependently." (PMID 27711186, 2016). "The EGFR was calculated with Cockcroft–Gault (CG), MDRD, MCQE and CKD-EPI, and classified as stages G1–G5 according to the Kidney Disease Improving Global Outcomes (KDIGO) GFR categories." (PMID 40363987, 2025). "Taken together, these results place EGFR as a mediator of ETV1 oncogenic activity both in early and advanced prostate carcinogenesis, while ERG overexpression seems to indirectly repress EGFR activation in early PCa carcinogenesis." (PMID 40808640, 2025). "Phase II studies, including the LUX-Bladder 1 trial (NCT02780687) and NCI-MATCH EAY131 basket trial, evaluated treatment with afatinib, a pan-HER TKI, and demonstrated mixed results in patients with HER2/3 mutations, while no responses were seen in 42 patients expressing HER1 (EGFR) mutations." (PMID 38675715, 2024).
renal failure (13 papers, 2013 to 2025). "Out of them, 5 developed severe adverse events related to the treatment, such as kidney failure, fatigue and nausea, moreover, 3 of these patients with severe side-effects did not go on to receive an EGFR TKI." (PMID 33652831, 2021).
rhabdomyosarcoma (13 papers, 2011 to 2025). A rare aggressive malignant mesenchymal neoplasm arising from skeletal muscle. "Flow cytometry confirmed the specific binding of fluorescently labeled eBAT to EGFR and uPAR expressing RD, a rhabdomyosarcoma cell line, and Saos2, an osteosarcoma cell line." (PMID 32630411, 2020). "We have demonstrated that tumors from our mouse model of alveolar rhabdomyosarcoma express EGFR at both the mRNA and protein levels." (PMID 21559212, 2011). "We then tested the EGFR inhibitor, Erlotinib, for its efficacy in this mouse model of alveolar rhabdomyosarcoma." (PMID 21559212, 2011). "Several studies, indeed, have shown that anti-EGFR-mediated neutralization of EGFR may result in effective growth inhibition of embryonal rhabdomyosarcoma cell lines in vitro." (PMID 26018798, 2015). "Moreover, EGFR-specific ITs were found to be effective in rhabdomyosarcoma cells." (PMID 40559886, 2025). "Moreover, it has been shown that epidermal growth factor receptor (EGFR) is highly expressed in embryonal rhabdomyosarcoma cells and thus may serve as a candidate therapeutic target." (PMID 26018798, 2015). "Flow cytometry confirmed the expression of both EGFR and uPAR in the RH30 rhabdomyosarcoma (RMS) cell line and the expression of only uPAR in the TC-71 Ewing sarcoma (EWS) cell line." (PMID 32630411, 2020). "Using flow cytometry, we identified a rhabdomyosarcoma (RMS) cell line, RH30, that expresses both uPAR and EGFR, and a Ewing sarcoma (EWS) cell line, TC-71, that expresses only uPAR." (PMID 29552283, 2018). "The receptor tyrosine kinase Epidermal Growth Factor Receptor (EGFR) has been found to be expressed and activated in human rhabdomyosarcomas." (PMID 21559212, 2011). "In contrast, EGFR (epidermal growth factor receptor), VEGFR2 (VEGF receptor 2 = KDR), and PDGFRA (platelet-derived growth factor receptor α) were overexpressed in embryonal, and ERBB3 (ErbB3) in alveolar and unclassified rhabdomyosarcomas." (PMID 23227212, 2012). "It should be noted that the rhabdomyosarcoma line, RH-30, has the same surface expression of IGF-1R and EGFR when examined by FACS (data not shown)." (PMID 23548153, 2013).
schwannoma (13 papers, 2006 to 2026). A benign, usually encapsulated slow growing tumor composed of Schwann cells. "EGFR overexpression has been documented in schwannoma tissue and is associated with proliferative activity, suggesting its potential as a therapeutic target." (PMID 41231782, 2025). "More importantly, the NRG1 ligand and its target the ERBB family receptors have been implicated in schwannoma tumorigenesis leading to preclinical testing of EGFR/ERBB2 kinase inhibitor lapatinib in a vestibular schwannoma model." (PMID 33273014, 2021). "We identified epidermal growth factor receptor (EGFR) signaling as a key driver of schwannoma growth and an escape mechanism from anti-IL6 treatment." (PMID 41758723, 2026). "Immunohistochemical staining of the schwannoma revealed the presence of the following: Calponin-1 (+), epidermal growth factor receptor (EGFR) (–), tumor protein 63 (P63) (–), and S-100 (+)." (PMID 34889239, 2021). "In contrast to ErbB2 and ErbB3, EGFR (another receptor of this family) was downregulated in schwannomas (−17.3-fold, p=2.26e-12)." (PMID 23354516, 2013). "In support of this notion, EGF, EGFR, TrkA/NGF receptor and the ligand NGF have been shown to bind to chromatins and Schwannoma-derived growth factor, a ligand for EGFR, bound to A+T-rich DNA sequences." (PMID 16434982, 2006). "Interestingly, previous reports have implicated overexpression of epidermal growth factor receptor family tyrosine kinases EGFR and ERBB2/HER2 in NF2-associated schwannomas and MN." (PMID 33273014, 2021). "The expression of EGFR seems to be restrained in schwannomas." (PMID 23354516, 2013). "Moreover, overexpression of miR-7 directly targeted and inhibited expression of Ack1, Pak1, and EGFR in schwannoma cells." (PMID 21454924, 2011). "Studies supporting a role for Pak1, EGFR, and Ack1 activation/overexpression in schwannoma growth, suggests alternative strategies and rationale for the development of new therapies for these tumors based on overexpression of miR-7 or inhibition of Ack1, Pak1, and EGFR pathways." (PMID 21454924, 2011). "We found that upregulated genes PIK3CG, CSF1R, SPP1, and CCND1 and downregulated genes EGFR and VWF were significantly enriched in PI3K-Akt signaling pathway involved in VSs development, which can increase schwannoma cell proliferation, survival, and cell-matrix adhesion acting." (PMID 32733557, 2020). "Given the fact that schwannomas, as many other cancers, are not always responsive to anti-EGFR treatment, our study suggests that Pak1 and/or Ack1 may prove critical therapeutic targets for schwannomas." (PMID 21454924, 2011). "However, its function as an activator of cell proliferation cannot be ruled out, since EGFR may still be signaling downstream in a merlin-absent context, despite the lack of proliferation of the human schwannoma cells following exposure to the ligand EGF, in contrast to non-tumoral vestibular cells." (PMID 23354516, 2013).
adenosquamous lung carcinoma (12 papers, 2014 to 2025). An aggressive carcinoma with a poor prognosis characterized by a presence of both malignant squamous cells and glandular cells. "In this case report, we describe a patient with EGFR-mutated lung adenosquamous carcinoma who exhibited persistent tumor progression despite multiple lines of therapy following resistance to third-generation EGFR-TKIs treatment." (PMID 41383506, 2025). "A previous study from Japan showed that approximately 21.9% out of 32 cases of adenosquamous cell carcinoma of the lung were positive for EGFR mutation." (PMID 29232915, 2017). "The frequency and clinicopathological characteristics of EGFR- and K-Ras-mutated adenosquamous lung carcinoma were similar to that noted in Asian adenocarcinomas patients." (PMID 26923333, 2016). "EGFR mutations are most common in adenocarcinoma, while their frequency in the context of adenosquamous lung carcinoma remains controversial." (PMID 27623437, 2016). "Adenosquamous lung carcinoma is an aggressive malignancy with relatively high EGFR mutation frequency." (PMID 27623437, 2016). "Although several small studies have indicated that the frequency of EGFR mutation in adenosquamous lung carcinoma ranges from 15% to 44% in the East Asian population, the exact prevalence of EGFR mutation in adenosquamous lung carcinoma is still not clear." (PMID 27623437, 2016). "The prognostic and predictive value of preoperative serum tumor markers and frequency of EGFR mutations in adenosquamous lung carcinoma are unclear." (PMID 27623437, 2016). "In another study of KRAS and EGFR mutations in adenosquamous lung carcinoma, one out of three tumors had an EGFR mutation detected only in the glandular (adeno) component and not in the squamous component." (PMID 24742923, 2014). "In addition, a prior study showed an adenosquamous lung carcinoma patient harboring EGFR-sensitizing mutation had a remarkable response to gefitinib." (PMID 27623437, 2016). "Of the 106 adenosquamous lung carcinoma patients, 29 (27.4%) harbored EGFR mutations." (PMID 27623437, 2016). "This article reports a rare case of a patient diagnosed with EGFR positive adenosquamous lung carcinoma, who experienced disease progression following treatment with Almonertinib." (PMID 40040728, 2025). "This article reports a patient with EGFR-mutant who achieved PR in the short term with monotherapy with ivonescimab after multiline therapy progression in advanced lung adenosquamous carcinoma." (PMID 41383506, 2025). "This study aimed to investigate the effect of Fuzheng Yiai Decoction (FZYA) on epidermal growth factor receptor-tyrosine kinase inhibitor (EGFR-TKI) drug resistance in lung adenosquamous carcinoma (ASC)." (PMID 39735556, 2024). "Median levels and positive rates for NSE, CEA, Cyfra21-1 or SCCA were similar regardless of EGFR mutation status in adenosquamous lung carcinoma patients." (PMID 27623437, 2016). "Therefore EGFR tyrosine kinase inhibitors would be a reasonable therapeutic option to adenosquamous lung carcinoma patients due to the relatively high frequency of EGFR mutations in this cohort." (PMID 27623437, 2016). "This case of exon 19 insertion is unique, as histology indicated adenosquamous cell carcinoma of the lung which is not commonly associated with EGFR mutation [Jänne and Johnson 2006] and uncertain data about the sensitivity of this mutation to TKIs." (PMID 25279299, 2014). "In addition, we did not investigate the adenosquamous lung carcinoma components separately so it is not known which harbored identified EGFR mutations." (PMID 27623437, 2016).
amyotrophic lateral sclerosis (12 papers, 2020 to 2025). Amyotrophic lateral sclerosis (ALS) is a neurodegenerative disease characterized by progressive muscular paralysis reflecting degeneration of motor neurons in the primary motor cortex, corticospinal tracts, brainstem and spinal cord. "Mutations in ErbB4 gene, encoding a member of the epidermal growth factor receptor, disrupt the Neuregulin-ErbB4 pathway, causing Amyotrophic Lateral Sclerosis (ALS), a neurodegenerative disease characterized by the loss of upper and lower motor neurons." (PMID 35409239, 2022). "C (mother), the top 30 signaling pathway results showed that proteins are mainly enriched in Fox O signaling pathway, PPAR signaling pathway, HIF-1 signaling pathway, Amyotrophic lateral sclerosis (ALS), EGFR tyrosine kinase inhibitor resistance etc.." (PMID 38802922, 2024). "In an in vitro model of amyotrophic lateral sclerosis (ALS), PACAP treatment of motor-neuron like cells mitigated cell death with its mechanism of action being the epidermal growth factor receptor (EGFR) and matrix metallopeptidase-2 (MMP-2) axis." (PMID 33653014, 2021). "KEGG analysis revealed two processes, Huntington’s disease and Amyotrophic lateral sclerosis, whereas the REACTOM database revealed one item: EGFR downregulation, with three genes, protein-tyrosine phosphatase (PTP)-PEST (PTPN12), epidermal growth factor receptor (EGFR), and epsin 1 (EPN1)." (PMID 40269194, 2025).